ENSG00000277577
Gene: Miscellaneous RNA gene on chromosome X (73,831,145 to 73,831,270, reverse strand). Ensembl gene ENSG00000277577.
Gene Ontology:
Biological process: dosage compensation by inactivation of X chromosome